DPH7 (diphthamide biosynthesis 7)
Description:
Catalyzes the demethylation of diphthine methyl ester to form diphthine, an intermediate diphthamide biosynthesis, a post-translational modification of histidine which occurs in translation elongation factor 2 (EEF2) which can be ADP-ribosylated by diphtheria toxin and by Pseudomonas exotoxin A (Eta).
Synonyms: C9orf112; WDR85; FLJ90634; RRT2
Tractability: PROTAC: ubiquitination databases record sites on it.
Gene: Protein-coding gene on chromosome 9 (137,554,444 to 137,578,925, reverse strand). Ensembl gene ENSG00000148399.
Subcellular location (Human Protein Atlas): Nuclear bodies
Pathways (Reactome):
Metabolism of proteins: Synthesis of diphthamide-EEF2
Gene Ontology:
Molecular function: protein binding; diphthine methylesterase activity
Biological process: protein histidyl modification to diphthamide
Cellular component: cytoplasm
Genetic constraint (gnomAD): Loss-of-function variants: 46 observed, 42.94 expected, observed/expected ratio (o/e) 1.07, 90% interval 0.85 to 1.37. The upper end of that interval is the gene's LOEUF score, 1.37, which puts it in group 5 of 6, group 1 being the genes least tolerant of losing a copy. Missense variants: 629 observed, 572.75 expected, observed/expected ratio (o/e) 1.1, 90% interval 1.03 to 1.17. Synonymous variants: 275 observed, 235.35 expected, observed/expected ratio (o/e) 1.17, 90% interval 1.06 to 1.29.
Homologues: Orthologues: chimpanzee DPH7 (99% identical), macaque DPH7 (92% identical), dog DPH7 (66% identical), rat Dph7 (66% identical), mouse Dph7 (65% identical), pig DPH7 (63% identical), guinea pig DPH7 (61% identical), tropical clawed frog dph7 (48% identical), zebrafish dph7 (47% identical), Drosophila melanogaster CG3184 (31% identical).
Diseases named in the same sentence as DPH7 in open-access papers:
DPH7 is named in the same sentence as 12 diseases in open-access papers, as found by Europe PMC text mining. Sharing a sentence is not in itself a finding about the gene and the disease. The quoted sentences say what the papers report.
ovarian carcinoma (1 paper, 2017). A malignant neoplasm originating from the surface ovarian epithelium. "Examples of DPH gene alterations include gene copy number changes (loss of heterozygosity, LOH) of the DPH1 (OVCA1) gene in ovarian cancers or a deletion of the DPH7 (WDR85) gene." (PMID 28245596, 2017).
DPH7 also shares sentences with these, for which no sentence is quoted: amyotrophic lateral sclerosis (1 paper); bacterial infections (1); cancer (1); colorectal cancer (1); dementia (1); diphtheria (1); endometrial cancer (1); infant botulism (1); Parkinson disease (1); primary bone cancer (1); tetanus (1).